CBX3 (chromobox 3)
Diseases named in the same sentence as CBX3 in open-access papers (continued):
Sharing a sentence is not in itself a finding about the gene and the disease.
tumor (continued). "Our research indicates that CBX3 might be used as a prognostic indicator for different malignant tumors due to its function in tumor genesis as well as tumor immunity." (PMID 35573019, 2022). "Additionally, the normal liver and pancreas tissue specimen depicted faint CBX3 staining, whereas tumor tissue depicted sturdy staining." (PMID 35573019, 2022). "Considering that CBX3 has a tumor-promoting effect in multiple tumors, we speculated that CBX3 might be involved in EC progression." (PMID 36140750, 2022). "Furthermore, as reported in the study by Lin and colleagues, CBX3 exerted pro-tumor function by promoting cell proliferation and the migration of GC cells." (PMID 36140750, 2022). "We found significantly increased mRNA expression of CBX3 in multiple tumor tissues." (PMID 35172803, 2022). "Additionally, CBX3 was significantly upregulated in tumor tissues compared with tumor-adjacent tissues in the TCGA-LUAD and CPTAC-LUAD datasets (all P < 0.001)." (PMID 34785774, 2022). "Furthermore, we discovered that the expression of CBX3 expression is related to age in certain tumor types." (PMID 35573019, 2022). "The findings from this research indicate that CBX3 could serve as a prognostic marker for different tumors, and has a crucial function in tumor immunity by influencing tumor-infiltrating immune cells (TIICs), MSI and TMB." (PMID 35573019, 2022). "In view of the role of CBX3/5/7 in tumor growth-related signaling pathways, the tumor immune microenvironment, and patient prognosis, we believe that CBX3/5/7 may be hub molecules of the CBX molecular family." (PMID 34966411, 2021). "In this study, we used clinical samples and in vitro studies to demonstrate that high expression of CBX3/5 in LUAD tissues promoted tumor cell proliferation and migration of tumor cells and promoted the infiltration of cytotoxic cells, CD8+ T cells, and other immune cells." (PMID 34966411, 2021). "On day 2, a subset of tumor-bearing Cbx3/HP1γ-deficient mice were treated with the blocking/non-depleting anti-mouse NKG2D antibody HMG2D, and thereafter once per week." (PMID 34721405, 2021). "Furthermore, KCNQ1OT1 exerted tumor promotion in HCC cells via suppressing miR-29a-3p to regulate CBX3 expression." (PMID 34008749, 2021). "Lef1- and Cbx3-Lef1-deficient mice, in which Tcf7 is not deleted, fail to control tumor growth suggesting that Lef1 function is not redundant." (PMID 34721405, 2021). "This experimental approach could be used to try to identify pools/genes that can accelerate (e.g. SATB2) or delay (e.g. CBX3) tumor onset." (PMID 33527896, 2021). "Furthermore, the elevated expression of HP1-γ (CBX3) has been demonstrated to exert impact on tumor diameter and lymph node metastasis." (PMID 34046352, 2021). "CBX3 has been reported to promote the proliferation, invasion, and migration of tumor cells." (PMID 33273987, 2020). "Univariate and multivariate survival analyses were conducted to determine whether high CBX3/HP1γ expression in tumor cells was an independent prognostic factor for HCC." (PMID 31375643, 2019). "This further demonstrated that CBX3 overexpression can increase tumor growth." (PMID 29903985, 2018). "In addition, expression of CBX3 is slightly associated with stage progress of PAAD, in which late stage patients seemed to have higher expression pattern of CBX3 in tumor tissues." (PMID 29903985, 2018). "In the present study, significantly higher mRNA and protein expressions of CBX3 were found in HCC tissues, and mRNA expression of CBX3 was dramatically associated with patients’ individual cancer stages and tumor grades which was consistent with the studies above." (PMID 30481161, 2018). "Together these changes in the tumor immune environment may have mitigated tumor burden in Cbx3/HP1γ-insufficient mice or wild type mice treated with Cbx3/HP1γ-insufficient CD8+ T cells." (PMID 28220815, 2017).
tumor (continued). "It is plausible that Cbx3/HP1γ-insufficient CD8+ effector T cells may alter the tumor microenvironment thus preventing CD4+ Treg infiltration." (PMID 28220815, 2017). "Here, we reveal a previously unknown and essential role for Cbx3/HP1γ in the control of tumor immunity." (PMID 28220815, 2017). "NB-9464 tumor-bearing Cbx3/HP1γ-insufficient mice survived longer than controls." (PMID 28220815, 2017). "By reducing the levels of Cbx3/HP1γ we can increase CD8+ effector T cells at the same time eliminate CD4+ Treg immune suppression in the tumor microenvironment that may control tumor growth." (PMID 28220815, 2017). "High CBX3 expression is observed in higher-grade tumors that exhibit stem cell-like traits, and CBX3-associated gene expression profiles are robustly enriched with stemness markers and targets for c-Myc transcription factor regardless of the tumor type." (PMID 36361869, 2022). "In addition, our analysis provided a potential mechanism that CBX3 might regulate the tumor immune microenvironment." (PMID 35172803, 2022). "Moreover, the enrichment analysis indicates that CBX3 may affect tumor etiology or pathogenesis through the following ways: cell cycle, signaling pathways, immune regulation, immune response, and B/T cell activation." (PMID 35573019, 2022). "Cbx3/HP1γ deficiency in CD4+ T cells did not enhance tumor cells killing." (PMID 34721405, 2021). "For instance, the association between the expression of target genes and tumor stemness score as well as with the drug sensitivity score indicated that CBX3 may mainly play tumor promotor roles during tumorigenesis as they are positively associated with tumor stemness and drug resistance scores." (PMID 33463006, 2021). "Our analysis uses a “prevalidation” integrated analysis to identify signatures and wet lab experiments to validate the identified CBX3 gene, which may accelerate translational research and will provide insight into new strategies to seek tumor biomarkers for precision oncology." (PMID 31138312, 2019). "GO and KEGG pathway analysis, as well as experimental observation showed that CBX3 may be associated with cell cycle transition of PAAD cells, and cyclin-dependent kinase 1 (CDK1) and proliferating cell nuclear antigen (PCNA) may mediate the tumor-promoting action of CBX3." (PMID 29903985, 2018). "We observed that CDK1 may mediate the tumor-promoting role of CBX3 in PAAD." (PMID 29903985, 2018). "Inhibition of CBX3 or lactate production has been found to reduce CD47 expression, restore phagocytic function, and inhibit tumor growth." (PMID 41463052, 2025). "A significant dysregulation was observed for CBX3, CBX4, and CBX8, all of which were upregulated in tumor tissues." (PMID 40806514, 2025). "In contrast, wild-type CCDC32 (possible tumor suppressor) decreased, with the CCDC32/CBX3 gene fusion unchanged." (PMID 39823827, 2025). "Other regulators of tumor biology, including PTPRS, CSPG4, SPRED1, CD59, and PROCR, were all downregulated upon CBX3 knockdown." (PMID 39545414, 2024). "Specifically, the CBX3-MAPK axis represents a potential therapeutic target, as the dysregulation of both CBX3 and MAPK pathways significantly contributes to tumor growth and survival." (PMID 39272883, 2024). "CBX3 knockdown in CW468 and GSC23 cells suppressed in vivo tumor growth, which translated into increased survival of tumor-bearing mice." (PMID 39545414, 2024). "Outside the CBX3/ARHGAP24/RAC1 axis, CBX3 can also facilitate smoking-induced LUAD by inhibiting the tumor suppressor FBP1 and controlling glycolysis." (PMID 39272883, 2024). "The oncogenic role of CBX3 is also highlighted by the observation that CBX3 and H3K9me3 levels are increased in NSCLC tumor-initiating cells, where they inhibit DNA damage responses to antineoplastic agents." (PMID 39272883, 2024).
tumor (continued). "The high expressions of the CBX family (including CBX2, CBX3, CBX5, and CBX6) in tumor tissues were related to the worse OS of DLBCL patients, whereas high expression of CBX1 was correlated with better prognosis of patients." (PMID 37430195, 2023). "We also unveiled that in addition to co-occurrence of gene amplification among CBX3, EGFR and RAC1, also low-grade CNVs of these genes strongly co-occur in several human tumor types and are much more recurrent than high-grade CNVs." (PMID 37633946, 2023). "The expression of CBX genes differs across solid tumors and for CBX1, CBX2, CBX3, CBX4, CBX5, and CBX8 is predominantly upregulated, while for CBX6 and CBX7 is mostly downregulated in tumor tissues." (PMID 36361869, 2022). "The highest mRNA levels of CBX3/8 were observed in tumor grade IV, whereas the highest mRNA levels of CBX6/7 were detected in tumor grade II." (PMID 35210369, 2022). "Taken together, these data suggested that the mRNA overexpression of CBX1, CBX3, and CBX8 were significantly related to tumor grades and patients’ tumor nodal metastasis status." (PMID 35464847, 2022). "In another 12 tumor types, including nodule COAD, READ, STAD, and UCEC, CBX3 expression correlates with MSI." (PMID 35573019, 2022). "Ultimately, we assessed the relationship between CBX3 expression and DSS to exclude non-tumor death factors." (PMID 35172803, 2022). "Specifically, we observed significant upregulation of CBX1, CBX3, and CBX5 members, followed by robust downregulation of CBX7 in tumor tissues." (PMID 36361869, 2022). "We observed significant positive correlation between a high CBX1, CBX2, CBX3, CBX5, and CBX8 expression and higher tumor grade in LIHC and UCEC tumors." (PMID 36361869, 2022). "The mRNA expression of CBX1, CBX2, CBX3, CBX4, and CBX8 tended to be elevated as the tumor grade increased." (PMID 35464847, 2022). "This strongly support our first observation of CBX3 being positively and CBX7 being negatively correlated with tumor stemness." (PMID 36361869, 2022). "Additionally, targeting the epigenetic machinery has been proven as an efficient anti-cancer strategy in several tumor types, albeit it remains an open question whether Cbx3/HP1γ or Cbx7 epigenetic factors could become novel therapeutic targets in stem cell-like tumors." (PMID 36361869, 2022). "Unexpectedly, the correlation analysis between the upstream regulator's analysis identified MYBL2, E2F2, CBX3, FOXM1, and E2F1, which were significantly elevated in the LUAD or LIHC tumor groups, with a strongly correlated value with utility as biomarkers." (PMID 35404841, 2022). "The results showed there was a trend for higher expression of CBX3 and CBX5 with the progression of LUAD, in terms of worse tumor grade, while the expression of CBX7 showed a decreasing trend." (PMID 34966411, 2021). "The expression levels of TMEM44, TMEM67, CBX3, and ELOVL3 in tumor tissue were higher than in normal tissue, which was consistent with the trend in EC." (PMID 33463006, 2021). "Removal of Cbx3/HP1γ restraint allows CD8+ T cells to become effector-like cells armed with an intrinsic heightened killing and persistence capacity to control tumor growth; LEF-1 function and IL-21R signaling are necessary." (PMID 34721405, 2021). "Hence we speculated that CBX3 may play a role in tumor immunity." (PMID 32894652, 2020). "Among them, chromobox protein homolog 3 (CBX3), which has the highest number of nodes related to survival-related immune genes, has been illustrated to promote tumor proliferation and predict poor survival in LIHC." (PMID 32191631, 2020). "The expression of CBX3 in CRC tissues was higher than that in normal tissues, and its expression was markedly correlated with clinical tumor stage in CRC patients." (PMID 33014884, 2020). "Next, we compared CBX3/HP1γ protein and RNA expression levels in three pairs of matched HCC tumor and adjacent non-tumor tissue using Western blots and qPCR." (PMID 31375643, 2019).
tumor (continued). "We extracted transcriptomic data of human PAAD tissue from GEO database and compared the expression of CBX3 in PAAD and non-tumor tissues from two datasets." (PMID 29903985, 2018). "Overexpression of CBX3 in PAAD cells was achieved by Crispr-cas9 activation, and in vitro and in vivo tumor cell growth and invasion was measured." (PMID 29903985, 2018). "To identify the clinical significance of CBX3 in PAAD, we first extracted expression data of CBX3 from two released GEO microarray datasets examining human PAAD and non-tumor pancreas transcriptomic profiles." (PMID 29903985, 2018). "Similar frequency of tumor-infiltrating ICOS+ CD4+ and ICOS+ CD8+ T cells was recovered from wt and Cbx3/HP1γ-insufficient mice." (PMID 28220815, 2017). "Our findings show that CBX3, CBX4, and CBX8, all members of the polycomb (Pc) group of the non-canonical PRC1 (nPRC1) complex, are significantly upregulated in both CRC cell lines and tumor tissues." (PMID 40806514, 2025). "CBX3 and CBX5 have been found to promote tumor cell proliferation and migration in vitro and regulate the expression of various cytokines that influence the tumor microenvironment." (PMID 40175347, 2025). "CBX3 and CD47 mRNA positively correlated in GBM datasets, while CBX3 negatively correlated with an immune score that represents immune cell infiltration in GBM tumor tissue." (PMID 39545414, 2024). "Strikingly, CBX3 deletion heightened CRC cells sensitivity to IFNγ, which ultimately enhanced their chemosensitivity under IFNγ stimulation in vitro with CRC cells and in vivo with a syngeneic mouse tumor model." (PMID 38684864, 2024). "This interconnection suggests that targeting CBX3 could disrupt the MAPK signaling cascade, potentially leading to reduced tumor proliferation and enhanced cancer cell apoptosis." (PMID 39272883, 2024). "ST1926 treatment down-regulated a group of oncogenic proteins (SLC2A1, SLC25A6, CBX3, DEK, DDX39B) and up-regulated a group of presumably tumor-suppressing proteins (PEBP1, HspBP1); PADI2 and CMPK1, of unknown function in GBM, were also up-regulated." (PMID 37762371, 2023). "Therefore, it is plausible to suggest that CBX3 initiates gene modifications that activate the PI3K signaling pathway, leading to immunological disorders and tumor growth in KIRC." (PMID 37674204, 2023). "Interestingly, we have also found that in cancer samples where CBX3 gene is amplified, there is also a statistically significant increase of RAC1 mRNA expression regardless the tumor tissue of origin." (PMID 37633946, 2023). "Similarly, mRNA expressions of CBX1, CBX2, CBX3, CBX4, and CBX8 were significantly related to patients’ tumor nodal metastasis status." (PMID 35464847, 2022). "For EC, CBX3 and CBX6 were significantly overexpressed in tumor tissues compared to normal tissues." (PMID 36140750, 2022). "Our results suggest a model whereby Cbx3/HP1γ normally restrains the effector and persistence potential of CD8+ T cells, which eventually succumb to functional inactivation and apoptosis thus incapable of controlling tumor development." (PMID 34721405, 2021). "Together, our results demonstrate that Cbx3/HP1γ-deficient CD8+ effector T cells expressing NKG2D can persist and cause tumor rejection, irrespective of tumor mutation status." (PMID 34721405, 2021). "We establish that genetic ablation of Cbx3/HP1γ induces the elevated, sustained expression of factors conferring both persistence and heightened effector/killing capacity on CD8+ T cells, which in turn enables them to control the growth of diverse tumor types." (PMID 34721405, 2021).
tumor (continued). "Genes CBX3, RCC1, TMOD3, and NOA1 (Cluster A) and TOP1, PDCD5, and THRAP3 (Cluster B) were upregulated for both datasets in PCa tissue vs. normal gland or normal adjacent to tumor tissue." (PMID 32640729, 2020). "Our study divulged that CBX3 mRNA expression was related with age, tumor diameter and lymph node metastasis, whereas no relation was found with sex, smoking history, histopathological classification, distant metastasis and TNM stage in the TCGA‐LUAD cohort." (PMID 32894652, 2020). "Based on our IHC scoring regime and the ROC curve cutoff value, patients were divided into low CBX3/HP1γ expression (negative or low expression in tumor cells) and high CBX3/HP1γ expression (high expression in tumor cells) groups." (PMID 31375643, 2019). "By contrast, tumors excised from wt or Cbx3/HP1γ-insufficient mice expressed similar levels of the stimulatory RAE-1 and inhibitory programmed cell death ligand 1 (PD-L1) ligands, both of which were induced in tumor cells." (PMID 28220815, 2017). "Therefore, we have further focused on CBX3 and CBX7 proteins, as their association with cancer stemness is most prominent and universal regardless of the tumor type." (PMID 36361869, 2022). "In addition to those tumors without normal tissue data to use, considerable differences in CBX3 expression were identified among 29 tumor tissues and non-tumor normal tissues." (PMID 35573019, 2022). "However, except for PRAD, most of the considerable differences in CBX3 expression occurred between stage-one and stage-four tumors, and the expression of CBX3 did not increase along with the increase of tumor stage." (PMID 35573019, 2022). "The exclusive increase of Cbx3/HP1γ-deficient CD8+ effector T cells in tumors and their subsequent disappearance when Lef1 is ablated suggest that LEF-1 is requisite for their persistence in varied tumor types irrespective of mutational status." (PMID 34721405, 2021). "It is not clear if Cbx3/HP1γ-insufficient CD8+ tumor T cells are reinvigorated TEX cells." (PMID 28220815, 2017). "Moreover, Cbx3/HP1γ insufficiency did not affect the generation of natural CD4+ Treg cells in tumor bearing mice." (PMID 28220815, 2017). "Because IL-21R expression is induced and sustained in Cbx3/HP1γ-deficient CD8+ effector T cells without exogenous IL-21, we posit that whether IL-21 production is high or low during tumor development, it can still positively affect Cbx3/HP1γ-deficient CD8+ T-cell effector functions." (PMID 34721405, 2021). "The remodelling of the tumour chemokine/receptor landscape and the increased persistence of CD8+ T cells lacking Cbx3/HP1γ allows their optimum invasion into tumours at the cost of CD4+ Tregs." (PMID 39169517, 2024). "Both CBX3/HP1γ protein and mRNA expression were elevated in HCC tumor tissues compared to matched adjacent nonneoplastic tissues." (PMID 31375643, 2019). "Finally, these genes were overlapped with the upregulated DEGs from the two GSE9782 datasets, resulting in 7 tumor stemness-related genes, including NONO, CBX3, SLC25A3, PTPRG, NPM1, HINT1, HNRNPA1." (PMID 41050668, 2025).